CCL8 (C-C motif chemokine ligand 8)
Diseases named in the same sentence as CCL8 in open-access papers (continued):
Sharing a sentence is not in itself a finding about the gene and the disease.
breast carcinoma (continued). "The specificity of this peptide was confirmed in vitro by testing the cytotoxic activity of breast cancer cells overexpressing CCR5, a major CCL8 receptor, and by a neutralizing anti‐CCL8 antibody we developed." (PMID 40545574, 2025). "C-C motif chemokine 8 (CCL8) is a member of the CC chemokine subfamily and plays a role in the migration and invasion of cancer cells in colorectal and breast cancers." (PMID 39475897, 2024). "Data from The Cancer Genome Atlas (TCGA) database demonstrated upregulation of CCL8 and TGFBI and downregulation of HGF in breast cancer." (PMID 37884960, 2023). "In the breast cancer mouse model, FMD treatment significantly reduced the increase of serum CCL8 of apatinib group." (PMID 37884960, 2023). "To further validate the clinical relevance of the SIGLEC1/CCL8 gene signature, we utilized the METABRIC cohort with 456 breast cancer-specific events over a median follow-up time of 9.69 years." (PMID 30930117, 2019). "In addition, multiplex IF staining of human liver metastases of breast cancer confirmed the correlation of NETs with CD68+ cells, DMBT1 and CCL8 expression." (PMID 40796724, 2025). "The premise of this hypothesis is that the receptors for CCL8, especially CCR2 and CCR5, are overexpressed in breast cancers, and thus, their presence sensitizes cells against specific receptor‐targeting moieties." (PMID 40545574, 2025). "Based on their functions in biology and carcinogenesis, the current results imply that serum CCL8, CCL23 and CCL28 could also be drivers of aggressive breast cancer behavior in situ." (PMID 38594742, 2024). "Stimulation with recombinant CCL8 (rCCL8) did not affect cell proliferation of either breast cancer cell line." (PMID 30930117, 2019). "Interestingly, a recent report suggests that CCL3 released from E0771 breast cancer cells increases expression of CCL7, CCL8, CCL11, and CCL12 in the lung." (PMID 30483271, 2018). "In addition, fluorescence in situ hybridization analysis of breast cancer tissue sections revealed that CCL8 mRNA is found in Br-TAM but not in cancer cells." (PMID 30930117, 2019). "In breast cancer, CCL8 enhances tumor cell activity and contributes to tumor metastasis by regulating the TME, and the pro-cancer effect of CCL8 is inhibited upon macrophage depletion, suggesting that CCL8 may promote tumor progression by recruiting macrophages." (PMID 36072582, 2022). "Since both cancer cells and cells of the microenvironment are responsive to CCL8, we sought to explore the effects of DTCCL8 in mouse breast cancer in mice that possess intact immune system, as opposed to human breast cancer xenografts at which the host's immune system is compromised." (PMID 40545574, 2025).
melanoma (23 papers, 2015 to 2025). A malignant, usually aggressive tumor composed of atypical, neoplastic melanocytes. "However, most of the currently available evidence in melanoma and other solid tumors is associative, and functional data demonstrating a causal role for CCL8 in modulating antitumor immunity are limited and sometimes contradictory." (PMID 41155258, 2025). "We also found genes that are associated with melanoma metastases formation (CCL8, CD38) and melanoma cell migration and invasion (KRT5)." (PMID 38671536, 2024). "CCL8 is involved in melanoma metastasis formation and the expression of this gene was found to be correlated with immune infiltration." (PMID 38671536, 2024). "Higher CCL8 expression was observed in baseline melanoma biopsies from patients with ICI resistance." (PMID 38155221, 2023). "The results showed that the expression of DSC3, DLL3, BMP6, SEMA4D, and GHRH are increased (p < 0.05) in melanoma, while the expression of LRRC4B, SFRP1, DCN, and CCL-8 decreased in melanoma (p < 0.05)." (PMID 36777724, 2023). "In the same study, four immune-related genes, HLA-B, HLA-DRA, CCL8, and IL2RA, have been shown to be associated with a good prognosis in melanoma." (PMID 36143291, 2022). "Conversely, the present study suggests that, at least in melanoma, CCL8 can play a protective role: high levels of CCL8 correlated with better prognosis." (PMID 34844613, 2021). "In melanoma, cell-to-cell communication in tumor cells impacts CCL8 expression patterns, thus building a microenvironment that facilitates tumor migration and metastasis." (PMID 33146700, 2020). "Dramatic increase of CCL8 expression was observed after melanoma and leukemia supernatant treatment, but in contrast 'pure' CCL8 treatment terminated the continuous expression of CCL8." (PMID 26320180, 2015). "Systemic appearance of CCL8 in the serum of patients with melanoma was analyzed by ELISA kit, with recombinant CCL8 used to set the standard curve." (PMID 26320180, 2015). "Examining the host-derived factors affecting the behavior of human melanoma in our experimental models, we have demonstrated CCL8 to have a regulatory role during melanoma progression." (PMID 26320180, 2015). "We then examined the expression of CCL8 in five, genetically different human melanoma cell lines (HT199, HT168M1, WM983A, A2058, WM983B) and found that it was expressed by only one of them (WM983B)." (PMID 26320180, 2015). "Cytoplasmic CCL8 also showed rich expression in melanoma tissue, which could induce increased cellular migration in tumor cell line." (PMID 36777724, 2023). "Then, we identified 9 LR pairs (“BMP6- > HJV” 、"CCL8- > ACKR4” 、"DLL3- > NOTCH3"、"DSC3- > DSG3"、"GHRH- > GHRHR” 、"LRRC4B- > PTPRF"、"SEMA4D- > PLXNB1"、"SFRP1- > FZD6"、"UCN- > CRHR1′′) as key LR pairs in melanoma prognosis through Lasso Cox regression and Multiple Stepwise Regression." (PMID 36777724, 2023). "CCL8 is also involved in promoting metastasis in mice inoculated with human melanoma cell lines." (PMID 34692697, 2021). "Moreover, in melanoma, previous research suggests that a local CCL8-rich environment promotes the selection of metastatic tumor cells, while a high CCL8 concentration inhibits their migration." (PMID 33428606, 2021). "This is in favor of the point that CCL8 in melanoma might play a protective role overall, of which the mechanism warrants further investigation." (PMID 32719391, 2020). "The role of CCL8 is controversial when it comes to melanoma." (PMID 32719391, 2020). "In conclusion, CCL8 may enhance the ability of metastasis formation in melanomas as a chemoattractant." (PMID 26320180, 2015). "Interestingly, an experiment in which melanoma cells were introduced into the bloodstream of mice while CCL8 and CCL15 were administered subcutaneously, resulted in an increased number of tumor cell colonies embedded in the lungs, suggesting important function of those chemokines in metastasis." (PMID 40725022, 2025).
melanoma (continued). "Interestingly, CCL8 has also been reported to inhibit melanoma metastasis, suggesting that its function may be highly variable across cancer types." (PMID 41561540, 2025). "CCL8 may enhance the ability of metastasis formation in melanomas as a chemoattractant." (PMID 33688507, 2021). "In contrast, our study developed a gene-based prognostic model to predict NK cell activation and melanoma prognosis, identifying CCNB1, PRKACB, FCGR2C, and CCL8 as key prognostic genes." (PMID 40430484, 2025). "We utilized the qRT-PCR method to explore CCL8, CXCL13 and IRF4 expression level in melanoma A375 cell lines and HFB4 control cell line." (PMID 38155221, 2023). "A study in 28 patients with metastatic melanoma previously reported that baseline melanoma biopsies from ICI-resistant patients display a higher expression of the MCP-2 coding gene (i.e., CCL8) compared to responding baseline tumours." (PMID 36007304, 2022). "In this study, 7 genes (CYTL1, CCL8, FCGR2C, OAS1, HAPLN3, WIPF1, CLIC2) were identified as prognostic signatures for melanoma." (PMID 33428606, 2021). "There was only one gene, CCL12 and its human homologue CCL8, which was expressed by only one human melanoma cell line (WM983B, which was derived from a melanoma metastasis) and therefore was proved to be suitable for further analysis." (PMID 26320180, 2015). "In studies using neuroblastoma and melanoma murine models, the absence of CD200/CD200R signaling (using CD200R- mice) caused TAMCs to upregulate CCL24 and CCL8 levels but downregulate the production of CXCL3, CXCL2, and CCL3." (PMID 38137547, 2023). "CCL8 is a potential prognostic marker for SKCM, and it may become an effective target for melanoma in which M1 macrophages play an important role." (PMID 34844613, 2021). "In clinical samples, when examining the tumor and the host together, the cumulative (tumor and host) CCL8 expression was lower in the group in which human primary melanoma formed lung metastasis compared to non-metastatic primary tumors." (PMID 26320180, 2015). "We also showed that, with the exception of one (WM983B), all the examined human melanoma cell lines lacked expression of CCL8, the human homologue of CCL12." (PMID 26320180, 2015). "When re-analyzing the data considering this subgroup, we found a significant difference between non-metastatic primary human melanoma and primary melanoma with lung metastases, the latter group expressing lower levels of CCL8." (PMID 26320180, 2015). "Altogether, 36 serum (17 metastatic and 19 non-metastatic) samples of patients with melanoma were analyzed and CCL8 protein concentration was higher than 60 pg/ml in 15(7 metastatic and 8 non-metastatic) of the analyzed serum samples." (PMID 26320180, 2015). "However, four genes, i.e., HPDL, GRIPAP1, GBP2, and TRIM34, have been reported to exhibit prognostic significance with respect to melanoma for the first time, while HAPLN3, CCL8, FCGR2A, and IFITM1 have been reported to relate with the initiation and immune microenvironment of cutaneous melanoma." (PMID 36818162, 2023). "Thus, the production of CCL24 and CCL8, and the reduction of CXCL3, CXCL2, and CCL3 in TAMCs, explain why mice lacking intact CD200/CD200R signaling more potently rejected neuroblastoma and melanoma tumors relative to wild-type conditions." (PMID 38137547, 2023). "They identified 10 genes (IL15, CCL8, CLIC2, SAMD9L, TLR2, HLA.DQB1, IGHV1–18, RARRES3, GBP4, APOBEC3G) involved in processes such as inflammation and immune response, which differentiate melanoma patients according to survival rate into two classes, with low and high risks." (PMID 36143291, 2022).
colitis (17 papers, 2015 to 2025). Inflammation of the colon. "By contrast, CCL8 overexpressing mice suffered from severe colitis characterized by profound loss of crypt structure, edema formation and inflammatory cell infiltrations." (PMID 33613532, 2020). "Recent research using a murine colitis model showed that CD169+ macrophages contribute to the accumulation of colitis-associated CD169− Ly6Chi CD64lo monocytes in the colon mucosa in a CCL8-dependent manner." (PMID 28751894, 2017). "CCL8 belongs to the CC chemokine subfamily and plays a pivotal role in various diseases, such as human immunodeficiency virus–associated dementia and visceral hypersensitivity induced by inflammatory bowel disease and colitis." (PMID 36136589, 2022). "In a mouse colitis model, CCL8 has been shown to be excreted exclusively by CD169+ macrophages, which in turn aids in the recruitment of monocytes to the LP under inflammatory conditions." (PMID 36982831, 2023). "The secondary BAs consistently showed a significant reduction in the mRNA levels of pro-inflammatory cytokines (Il6, Il1β, Tnfα) and some monocytes-related chemokines (Ccl2, Ccl7, Ccl8) in colitis mice." (PMID 36050867, 2022). "In this study here, we explored the functional role of the CC chemokine receptor CCR8 and its activation by the two known ligands CCL1 and CCL8 in DSS colitis, a widely used mouse model of IBD resembling important features of UC." (PMID 33613532, 2020). "To ascertain the individual capacity of both CCR8 ligands to regulate mucosal damage during acute colitis, we studied in the next series of experiments the development of DSS colitis in the absence or presence of systemic CCL1 or CCL8 overexpression." (PMID 33613532, 2020). "CCL8 production also sustains colitis induced by dextran sulfate sodium treatment and to recruit pro-inflammatory monocytes to the inflamed site." (PMID 30930117, 2019). "The results derived from the DSS-induced colitis model mouse suggested the chemoattractive effect of CCL8 on monocytes and macrophages." (PMID 26193821, 2015). "Selective depletion of CD169+ macrophages or administration of neutralizing anti-CCL8 antibody ameliorates the symptoms of experimentally induced colitis in mice." (PMID 26193821, 2015). "Using this ELISA, we found that the amount of CCL8 in the culture medium of colon explant resected from the colitis mouse was increased by more than 3-fold compared with that of naive colon." (PMID 26193821, 2015). "Here, the authors identify CD169+ macrophages as contributors to the inflammation of DSS colitis through their role in mediating the recruitment of monocytes by secreting the cytokine CCL8." (PMID 26193821, 2015). "The identification of CCL8 as a cytokine produced exclusively by CD169+ macrophages under the inflammatory condition prompted us to neutralize this molecule in vivo in colitis mice." (PMID 26193821, 2015). "In addition, the mRNA levels of proinflammatory cytokines including Ccl5, IL-17, IL-6, TNF-α, IFN-γ, CXCL10, and Ccl8 were all found to be increased in colitis tissues of S100A4Smad4-/- mice compared with those in Smad4fl/fl mice." (PMID 39664586, 2024). "Similarly, CCL8 expression in the course of DSS colitis was localized to intestinal macrophages in earlier studies." (PMID 33613532, 2020). "Moreover, increased CCL1 and CCL8 protein concentrations were present in supernatants of stimulated lamina propria mononuclear cells (LPMCs) isolated from mice with DSS colitis." (PMID 33613532, 2020). "Interestingly, further experiments clearly suggested that these CCR8-mediated tissue protective effects are exclusively mediated by the ligand CCL1, while CCL8-treatment of wildtype mice rather exacerbated colitis." (PMID 33613532, 2020). "In further experiments, we also analyzed, whether increased in vivo concentrations of CCL1 or CCL8 affected the mucosal frequencies of IFN-γ producing ILCs in the lamina propria of mice with DSS colitis." (PMID 33613532, 2020).
colitis (continued). "In colon, CD169+ macrophage mainly located in laminar propria could produce CCL8 in response to epithelial injury to initiate colitis by recruiting inflammatory monocytes." (PMID 28694804, 2017). "Treatment with anti-CCL8-neutralizing antibody suppressed clinical symptoms of DSS-induced colitis." (PMID 26193821, 2015). "Notably, the administration of neutralizing anti-CCL8 antibody improves the clinical symptoms of DSS-induced colitis in mouse." (PMID 26193821, 2015). "We further tried to examine CCL8 protein levels in the DSS-induced colitis mouse." (PMID 26193821, 2015). "In contrast, anti-CCL8 antibody ameliorated the clinical symptoms of DSS-induced colitis." (PMID 26193821, 2015). "Furthermore, the interaction between CCL8 and its putative receptor, CCR5, in the spinal cord has been shown to influence the development of visceral hyperalgesia in a murine colitis model, which could potentially also be the cause of persistent pain found in IC/BPS." (PMID 36982831, 2023). "CCL2, CCL8, and CXCL10 have been described to recruit inflammatory monocytes and macrophages or Th1 cells to promote colitis, respectively." (PMID 35463017, 2022). "Several genes such as Gata3, Itk, Ccl8, Ccl22, Ccr4, Crlf2, Il9r, Il1rl1, and Arg2 are regulated concordantly in T-cell transfer colitis, acute DSS colitis and the time point representing high inflammation in the DSS time course." (PMID 34136502, 2021). "As in murine colitis, CCL7, CCL8, and CXCL1 were all significantly increased in active IBD vs. quiescent IBD and controls." (PMID 30542349, 2018). "The importance of CCL7, CCL8, CCL12, and CXCL1 to mediate colitis inflammation, and the consequence of enhanced monocyte expression of these chemokines on pathology, is not known." (PMID 30542349, 2018). "A range of monocyte and neutrophil attracting chemokines (Ccl7, Ccl8, Cxcl1) were more highly expressed in macrophages compared to monocytes from both steady state and DSS colitis." (PMID 30542349, 2018). "CCL8 is expected to play a pro-inflammatory role, as it induces the migration of CD4+ T cells to the skin in a chronic atopic dermatitis model and the migration of macrophages to the inflamed intestine in a dextran sulfate sodium–induced colitis model." (PMID 37567910, 2023). "In the present study, the administration of anti-CCL8 antibody did not completely suppress the symptoms of DSS-induced colitis as compared with the depletion of CD169+ macrophages." (PMID 26193821, 2015). "However, in contrast to our present findings, a previous study indicated that CD169+ macrophages promote colitis by secreting CCL8 rather than CCL1234." (PMID 41429897, 2025). "In this setting, CCL8 treatment resulted in increased colitis even in the absence of CCR8 supporting the concept that this chemokine seemingly at least under these particular experimental settings employs other CCR8 independent signal transduction pathways to amplify intestinal inflammation in vivo." (PMID 33613532, 2020). "Although it has been reported that CD169+ macrophages express Ccl2, Ccl7, and Ccl8 during colitis (the contribution of monocytes was not considered), and analysis of colon IBD sections has suggested CCL8 as the greatest up-regulated chemokine released from inflammatory cells." (PMID 30542349, 2018).